PIAS2 (protein inhibitor of activated STAT 2)
Description:
Functions as an E3-type small ubiquitin-like modifier (SUMO) ligase, stabilizing the interaction between UBE2I and the substrate, and as a SUMO-tethering factor. The effects of this transcriptional coregulation, transactivation or silencing may vary depending upon the biological context and the PIAS2 isoform studied. However, it seems to be mostly involved in gene silencing. Binds to sumoylated ELK1 and enhances its transcriptional activity by preventing recruitment of HDAC2 by ELK1, thus reversing SUMO-mediated repression of ELK1 transactivation activity. Isoform PIAS2-beta, but not isoform PIAS2-alpha, promotes MDM2 sumoylation. Isoform PIAS2-alpha promotes PARK7 sumoylation. Isoform PIAS2-beta promotes NCOA2 sumoylation more efficiently than isoform PIAS2-alpha. Isoform PIAS2-alpha sumoylates PML at'Lys-65' and 'Lys-160'.
Synonyms: ARIP3; DIP; Miz1; PIASX; PIASX-BETA; miz; PIASX-ALPHA; ZMIZ4; SIZ2
Tractability: PROTAC: UniProt records ubiquitination sites on it; ubiquitination databases record sites on it.
Gene: Protein-coding gene on chromosome 18 (46,803,218 to 46,920,160, reverse strand). Ensembl gene ENSG00000078043.
Subcellular location: Nucleus speckle; Nucleus, PML body; Nucleus
Subcellular location (Human Protein Atlas): Nucleoplasm
Pathways (Reactome):
Metabolism of proteins: SUMOylation of DNA damage response and repair proteins; SUMOylation of chromatin organization proteins; SUMOylation of intracellular receptors; SUMOylation of transcription cofactors; SUMOylation of transcription factors; SUMOylation of ubiquitinylation proteins
Developmental Biology: Activation of anterior HOX genes in hindbrain development during early embryogenesis
Gene Ontology:
Molecular function: protein binding; RNA polymerase II-specific DNA-binding transcription factor binding; SUMO ligase activity; SUMO transferase activity; transcription coregulator activity; transcription regulator inhibitor activity; zinc ion binding; DNA binding; ubiquitin protein ligase binding
Biological process: negative regulation of androgen receptor signaling pathway; protein sumoylation; negative regulation of receptor signaling pathway via JAK-STAT; regulation of transcription by RNA polymerase II
Cellular component: nucleoplasm; nucleus; PML body; chromatin; nuclear speck
Genetic constraint (gnomAD): Loss-of-function variants: 8 observed, 45.61 expected, observed/expected ratio (o/e) 0.18, 90% interval 0.1 to 0.32. The upper end of that interval is the gene's LOEUF score, 0.32, which puts it in group 1 of 6, group 1 being the genes least tolerant of losing a copy. Missense variants: 474 observed, 607.19 expected, observed/expected ratio (o/e) 0.78, 90% interval 0.72 to 0.84. Synonymous variants: 205 observed, 219.32 expected, observed/expected ratio (o/e) 0.93, 90% interval 0.83 to 1.05.
Homologues: Orthologues: chimpanzee PIAS2 (100% identical), macaque PIAS2 (98% identical), mouse Pias2 (98% identical), pig PIAS2 (97% identical), rat Pias2 (97% identical), dog PIAS2 (97% identical), rabbit PIAS2 (89% identical), tropical clawed frog pias2 (72% identical), zebrafish pias2 (71% identical), Drosophila melanogaster Su(var)2-10 (36% identical). Paralogues in human: PIAS1 (59% identical), PIAS3 (55% identical), PIAS4 (38% identical), ZMIZ2 (23% identical), ZMIZ1 (22% identical).
Diseases named in the same sentence as PIAS2 in open-access papers:
PIAS2 is named in the same sentence as 34 diseases in open-access papers, as found by Europe PMC text mining. Sharing a sentence is not in itself a finding about the gene and the disease. The quoted sentences say what the papers report.
Cognitive impairment (2 papers, 2021 to 2023). Abnormal cognition is characterized by deficits in thinking, reasoning, or remembering. "To determine its function in brain, we overexpressed PIAS2 under a neuronal promoter, alone or with human α-synuclein, in the brains of mice, which caused motor and cognitive impairments and correlated with intraneuronal phosphorylated (p)α-synuclein accumulation and dopaminergic neuron loss." (PMID 34234281, 2021). "We next established that high expression of neuronal PIAS2 in vivo was sufficient to cause PDD-like pathology, and behavioral defects including cognitive impairments in healthy mice." (PMID 34234281, 2021).
melanoma (2 papers, 2024 to 2025). A malignant, usually aggressive tumor composed of atypical, neoplastic melanocytes. "This concurs with findings that the TRAF2/PIAS2/ELAVL1/EPHA5 pathway is pivotal in IL-17A-induced melanoma." (PMID 40809015, 2025). "IL-17A stimulation recruits ELAVL1 and PIAS2 via TRAF2, stabilizing EPHA5 mRNA and promoting melanoma cell proliferation and invasion." (PMID 40809015, 2025). "Induces EPHA5 via TRAF2 to recruit PIAS2 and ELAVL1 to promote melanoma development." (PMID 39906741, 2024). "IL-17 also induces EPHA5 via TRAF2 to recruit PIAS2 and ELAVL1 to promote melanoma development." (PMID 39906741, 2024).
papillary thyroid carcinomas (2 papers, 2024). "Among these, PIAS2 is highly expressed in differentiated papillary thyroid carcinomas but significantly reduced in anaplastic thyroid carcinomas (ATC), a highly lethal, undifferentiated cancer." (PMID 39457720, 2024). "The E3 SUMO ligase PIAS2 is expressed at high levels in differentiated papillary thyroid carcinomas but at low levels in anaplastic thyroid carcinomas (ATC), an undifferentiated cancer with high mortality." (PMID 38744818, 2024). "A comprehensive analysis of the expression of SUMOylation machinery components in papillary thyroid cancer (PTC) reveals the significant deregulation of SENP8, ZMIZ1, SAE1, PIAS1, and PIAS2 in most cases." (PMID 39457720, 2024).
Arthritis (1 paper, 2025). Inflammation of a joint. "Curcumin attenuated the severity of arthritis and reduced synovial hyperplasia by modulating the inc00052/miR-126-5p/PIAS2 pathway through the JAK2/STAT3 signaling mechanism, thereby providing protective effects against RA." (PMID 39974740, 2025).
autism spectrum disorder (1 paper, 2020). A spectrum of developmental disorders that includes autism, and Asperger syndrome.
bladder cancer (1 paper, 2024). "PIAS2 was a protective effect on the prognosis of bladder cancer (OS, DSS), colorectal cancer (DFS, DSS) and brain cancer (OS), but acted as a disadvantage prognostic factor in breast cancer (RFS), lung cancer (OS, RFS) and skin cancer (OS)." (PMID 38528630, 2024).
cervical carcinoma (1 paper, 2015). A carcinoma arising from either the exocervical squamous epithelium or the endocervical glandular epithelium. "Colocalization between PIAS2 and UXT was identified in the nucleus and cytoplasm of HEK 293T and human cervical carcinoma HeLa cells." (PMID 25434787, 2015).
cognitive decline (1 paper, 2021). "Neuronal expression of PIAS2 in the SN, STR, and prefrontal cortex of WT mice caused significant behavioral defects, including movement disorders, cognitive decline, and the loss of dopaminergic neurons—main hallmarks of PDD." (PMID 34234281, 2021). "Furthermore, we observed that PIAS2 has a negative impact on neuronal action potentials, which is compatible with its potential role in driving the cognitive decline in sPDD." (PMID 34234281, 2021).
glioma (1 paper, 2025). A benign or malignant brain and spinal cord tumor that arises from glial cells (astrocytes, oligodendrocytes, ependymal cells). "Immune-related pathways such as TNF signalling (IDH3B/G, MDH1, ACO2, SDHA, OGDHL) and JAK/STAT3 (PIAS2/3, PTPN2, AKT1/2, MCL1, CISH, AOX1) signalling are enriched in gliomas and play a critical role in their progression." (PMID 41007296, 2025).
HCMV infection (1 paper, 2024). "WT HCMV infection also substantially increased the accumulation of PIAS-type E3-SUMO ligases, including PIAS1, PIAS3, and PIAS4, as well as PIAS2, albeit to a much lesser extent." (PMID 38768227, 2024).
non-small cell lung carcinoma (1 paper, 2022). A group of at least three distinct histological types of lung cancer, including non-small cell squamous cell carcinoma, adenocarcinoma, and large cell carcinoma. "PIAS2 regulates the IFN-gamma signaling pathway, affecting tumor development in non-small-cell lung cancer." (PMID 35637462, 2022).
Parkinson disease dementia (1 paper, 2021). "Overexpression of PIAS2 alone was sufficient to cause PD-like dementia and major pathological trademarks of PDD in mice, whereas its knockdown in vivo reversed the PD-like dementia and pathology in Ifnb–/– mice, implicating it as a driver of PD pathology." (PMID 34234281, 2021). "Based on these findings, our newly identified dysfunctional type 1 IFN signaling pathway, via PIAS2, is the first revelation of the involvement of an entire signaling cascade in the evolution of PD, including its development to dementia." (PMID 34234281, 2021). "There are little data on the involvement of PIAS2 in PD pathology, and its contribution to PD and dementia has not been established." (PMID 34234281, 2021).
thyroid cancer (1 paper, 2024). "Thus, we explored if PIAS2 has a specific role in thyroid cancer." (PMID 38744818, 2024). "We find that the PIAS2 protein significantly increased in differentiated PTC cultures and thus have studied PIAS2 and its isoforms, across the entire range of follicular-lineage thyroid neoplasms, to see if it plays a role in thyroid cancer." (PMID 38744818, 2024).
virus infection (1 paper, 2014). "In duck cells, expression of IFNAR1, PIAS2 and STAT-3 was up-regulated by LPAI H2N3 or H5N1-tyEng91 virus infection." (PMID 25431115, 2014).
cancer (6 papers, 2019 to 2024). A tumor composed of atypical neoplastic, often pleomorphic cells that invade other tissues. "PIAS2 expression was significantly decreased in six cancer types and significantly elevated in six cancer types." (PMID 38528630, 2024). "PIAS2 is also dysregulated in thyroid cancer, and in other cancer types like GC, HCC, leukemia, ovarian, renal, sarcoma and testicular, it has been shown genetic alterations of this ligase that can contribute to cancer progression." (PMID 35887358, 2022). "Few exceptions include SENP2 and PIAS2, which consistently show downregulated expression in cancer cells and correlate with better prognosis when overexpressed." (PMID 35887358, 2022). "However, after 10 passages, the T-PIAS2 shRNA cells lost the ability to reduce PIAS2 expression and the anti-cancer effect, and this prevented further use of these cell populations." (PMID 38744818, 2024). "In this study, we analyzed the expression of PIAS family genes (PIAS1, PIAS2, PIAS3, and PIAS4) in 33 different types of cancer." (PMID 38528630, 2024).
infection (4 papers, 2014 to 2025). The state of being infected such as from the introduction of a foreign agent such as serum, vaccine, antigenic substance or organism. "Similarly, H5N1 subtype AIV infection promotes the expression of duck PIAS2 in duck embryo fibroblast cells." (PMID 41413919, 2025). "Following 24 h of infection with H5N1-tyEng91 or H5N1-tyTR05 virus, members of JAK-STAT signalling pathway (JAK1, IFN-α receptor 1 [IFNAR1], STAT-3 and protein inhibitor of activated STAT 2 [PIAS2]) were down-regulated in chicken cells." (PMID 25431115, 2014).
tumor (2 papers, 2022 to 2024). "The overall expression of PIAS2 and PIAS4 in tumor should be described more in detail." (PMID 38590645, 2024).
bone disorder (1 paper, 2022). "Moreover, dysregulated PIAS2 expression induces the development of bone disorders." (PMID 35473503, 2022).
brain disease (1 paper, 2015). "Moreover, 10 genes (ATP1A1, ATP6V1D, C16orf45, CROCC, KLC1, LUC7L2, PIAS2, PRKAR1B, RBFOX1, and RPL19) interacts with at least one brain disease-associated gene." (PMID 26043779, 2015).
PIAS2 also shares sentences with these, for which no sentence is quoted: anaplastic thyroid carcinomas (1 paper); brain cancer (1); breast carcinoma (1); colorectal cancer (1); gastric tumor (1); Intellectual disability (1); ischemia reperfusion injury (1); lung adenocarcinoma (1); lung carcinoma (1); meningioma (1); movement disorder (1); Parkinson disease (1); rheumatoid arthritis (1); skin cancer (1); thyroid neoplasms (1).